OSGIN1 (oxidative stress induced growth inhibitor 1)
Description:
Monooxygenase catalytic activity. Involved in regulation of cytokinesis; promotes RHOA activity, probably acting locally at the midbody in late cytokinesis. Monooxygenase activity is involved in stabilizing transient structures between daughter cells, termed intercellular bridges, before abscission. Regulates differentiation and proliferation through the regulation of cell death.
Synonyms: BDGI; OKL38
Tractability: PROTAC: ubiquitination databases record sites on it.
Gene: Protein-coding gene on chromosome 16 (83,931,311 to 83,966,333, forward strand). Ensembl gene ENSG00000140961.
Subcellular location: Midbody
Subcellular location (Human Protein Atlas): Cytosol; Nucleoplasm
Gene Ontology:
Molecular function: growth factor activity; protein binding
Biological process: negative regulation of cell growth; signal transduction
Cellular component: midbody
Genetic constraint (gnomAD): Loss-of-function variants: 21 observed, 21.08 expected, observed/expected ratio (o/e) 1, 90% interval 0.71 to 1.43. The synonymous counts are far from expectation, so gnomAD's model fits this gene poorly and the ratio says little. Missense variants: 813 observed, 649.44 expected, observed/expected ratio (o/e) 1.25, 90% interval 1.18 to 1.33. Synonymous variants: 367 observed, 301.68 expected, observed/expected ratio (o/e) 1.22, 90% interval 1.12 to 1.33.
Homologues: Orthologues: chimpanzee OSGIN1 (99% identical), macaque OSGIN1 (96% identical), dog OSGIN1 (88% identical), pig OSGIN1 (88% identical), rat Osgin1 (82% identical), mouse Osgin1 (82% identical), guinea pig OSGIN1 (80% identical), tropical clawed frog osgin1 (59% identical), Caenorhabditis elegans osgn-1 (28% identical). Paralogues in human: OSGIN2 (50% identical).